ZBTB1 (zinc finger and BTB domain containing 1)
Description:
Acts as a transcriptional repressor. Represses cAMP-responsive element (CRE)-mediated transcriptional activation. In addition, has a role in translesion DNA synthesis. Requires for UV-inducible RAD18 loading, PCNA monoubiquitination, POLH recruitment to replication factories and efficient translesion DNA synthesis. Plays a key role in the transcriptional regulation of T lymphocyte development (By similarity).
Synonyms: KIAA0997; ZNF909
Tractability: PROTAC: UniProt records ubiquitination sites on it; ubiquitination databases record sites on it.
Target class: Transcription factor
Gene: Protein-coding gene on chromosome 14 (64,502,152 to 64,533,690, forward strand). Ensembl gene ENSG00000126804.
Subcellular location: Nucleus; Nucleus, nucleoplasm
Subcellular location (Human Protein Atlas): Nucleoplasm; Nuclear membrane
Gene Ontology:
Molecular function: K63-linked polyubiquitin modification-dependent protein binding; protein binding; protein heterodimerization activity; protein homodimerization activity; DNA-binding transcription repressor activity, RNA polymerase II-specific; RNA polymerase II cis-regulatory region sequence-specific DNA binding
Biological process: cellular response to UV; chromatin remodeling; DNA damage response; DNA repair; mRNA transcription by RNA polymerase II; negative regulation of transcription by RNA polymerase II; protein homooligomerization; translesion synthesis; positive regulation of natural killer cell differentiation; positive regulation of pro-T cell differentiation; positive regulation of T cell differentiation; positive regulation of T cell mediated immunity; regulation of cytokine production; regulation of immune system process; thymus development
Cellular component: nuclear body; nucleoplasm; nucleus
Genetic constraint (gnomAD): Loss-of-function variants: 13 observed, 54.19 expected, observed/expected ratio (o/e) 0.24, 90% interval 0.16 to 0.38. The synonymous counts are far from expectation, so gnomAD's model fits this gene poorly and the ratio says little. Missense variants: 567 observed, 902 expected, observed/expected ratio (o/e) 0.63, 90% interval 0.59 to 0.67. Synonymous variants: 240 observed, 300.07 expected, observed/expected ratio (o/e) 0.8, 90% interval 0.72 to 0.89.
Homologues: Orthologues: pig ZBTB1 (98% identical), dog ZBTB1 (97% identical), guinea pig ZBTB1 (96% identical), mouse Zbtb1 (95% identical), rat Zbtb1 (93% identical), chimpanzee ZBTB1 (90% identical), macaque ZBTB1 (89% identical), rabbit ZBTB1 (79% identical), tropical clawed frog ppp1r36 (59% identical), zebrafish zbtb1 (48% identical). Paralogues in human: ZBTB18 (16% identical), ZBTB42 (14% identical), HIC1 (13% identical), HIC2 (12% identical), ZBTB16 (12% identical), PATZ1 (11% identical), PRDM14 (11% identical), ZNF451 (10% identical), PRDM10 (10% identical), PRDM1 (10% identical), ZBTB20 (10% identical), ZBTB7C (10% identical), and 24 more.
Diseases named in the same sentence as ZBTB1 in open-access papers:
ZBTB1 is named in the same sentence as 17 diseases in open-access papers, as found by Europe PMC text mining. Sharing a sentence is not in itself a finding about the gene and the disease. The quoted sentences say what the papers report.
breast carcinoma (4 papers, 2021 to 2025). "In fact, ZBTB1 has been recently associated with resistance to tamoxifen and aerobic glycolysis in breast cancer cells." (PMID 34944947, 2021). "ZBTB1 has been shown to suppress glucose uptake and counteract aerobic glycolysis in breast cancer cells." (PMID 40861257, 2025). "MiR-23b-3p inhibits breast cancer cell proliferation and tumor growth by targeting Zbtb1 to regulate aerobic glycolysis in tamoxifen-resistant cells." (PMID 34290994, 2021). "However, ZBTB1 is directly targeted by mirtron hsa-mir-1229–3p, which is upregulated in breast cancers." (PMID 40861257, 2025). "Re-expression of ZBTB1 in HER2-expressing breast cancer cell lines reduced lactate production, glucose uptake, and down-regulated LDH and HK expression, indicating that the elevated expression of HER2 due to the loss of ZBTB1 promotes aerobic glycolysis." (PMID 34208071, 2021). "Some studies have shown that Zbtb1 is a tumor suppressor in breast cancer cells." (PMID 34290994, 2021). "Additionally, in breast cancers, the tumor suppressor zinc finger and BTB domain containing 1 (ZBTB1) has been identified as a direct target of mirtron hsa-mir-1229–3p." (PMID 40861257, 2025).
Immunodeficiency (3 papers, 2022 to 2025). Failure of the immune system to protect the body adequately from infection, due to the absence or insufficiency of some component process or substance. "In another model, Zbtb1 was unexpectedly found as an insertion site of a transgene, which led to the T−B+NK− severe combined immunodeficiency phenotype." (PMID 36126774, 2022).
T cell deficiency (2 papers, 2021 to 2023). "Of note, despite the similar extent of T-cell deficiency, ZBTB1-knockout mice have increased numbers of short-term HSCs, multi-potent progenitors and CLPs, while scanT mice with a single substitution of the conserved cysteine (C47R) in the BTB domain of ZBTB1 do not." (PMID 34349770, 2021).
T-cell lymphoma (2 papers, 2021 to 2024). "This study describes the differentially expressed microRNA and circRNA in normal and Zbtb1-deficient EL4 cell lines, thus providing potential targets for drug development and clinical treatment of T-cell lymphoma." (PMID 34290994, 2021). "However, the role of Zbtb1 in T-cell lymphoma is undetermined." (PMID 34290994, 2021).
age (1 paper, 2025). A temporal measurement of the time period elapsed since an identifiable point in the life cycle of an organism. "Future work will also address whether ZBTB1 could be used to augment the generation of mature lymphoid lineages from human BM precursors, with potential therapeutic implications for addressing age-related immune decline." (PMID 40615375, 2025).
gastric cancer (1 paper, 2022). A primary or metastatic malignant neoplasm involving the stomach. "Especially, with regard to EMT process, several articles demonstrated the important roles of m6A regulation on SNAI1 in HeLa and HepG2 cells, GFI1 and ZMYM1 in gastric cancer cells, AXL in ovarian cancer cells, and ZBTB1 in bronchial epithelial cells." (PMID 36183833, 2022).
leukemia (1 paper, 2023). A malignant (clonal) hematologic disorder, involving hematopoietic stem cells and characterized by the presence of primitive or atypical myeloid or lymphoid cells in the bone marrow and the blood. "Zinc finger and BTB domain-containing protein 1 (ZBTB1) promotes ASNS expression by binding the promoter of ASNS, which mediates the sensitivity of leukemia cells to L-asparaginase." (PMID 37528150, 2023).
cancer (3 papers, 2015 to 2021). A tumor composed of atypical neoplastic, often pleomorphic cells that invade other tissues. "Zbtb1 not only plays an important role in lymphocyte development but has also been associated with cancer and DNA damage repair." (PMID 34956935, 2021).
bacterial infections (1 paper, 2017). "To investigate if Zbtb1 was required for the function of ILC3 cells in protecting mice from bacterial infections, we evaluated if ScanT mice were more susceptible to C. rodentium infections." (PMID 28915559, 2017).
ZBTB1 also shares sentences with these, for which no sentence is quoted: tumor (3 papers); breast tumors (1); eczema (1); infection (1); ovarian carcinoma (1); pancreatic cancer (1); psoriasis (1); T-cell leukemia (1).